CSTB (cystatin B)
Diseases named in the same sentence as CSTB in open-access papers (continued):
Sharing a sentence is not in itself a finding about the gene and the disease.
ovarian carcinoma (7 papers, 2010 to 2025). A malignant neoplasm originating from the surface ovarian epithelium. "Dysregulated expression of CSTB has been implicated to be a useful biomarker in various cancers such as ovarian cancer, esophageal cancer and breast cancer." (PMID 31139015, 2019). "Our data suggest that CSTB is tumor tissue-specific and a potential diagnostic marker for ovarian cancer." (PMID 24452274, 2014). "CSTB may become a novel diagnostic intracellular biomarker for the early detection of ovarian cancer." (PMID 24452274, 2014). "Previous studies have shown that CSTB plays different roles in ovarian cancer, colon cancer, and myoclonic epilepsy." (PMID 35488257, 2022). "Our in vitro study showed that CSTB expression in two epithelial ovarian cancer cell lines was decreased after TGF-β1 treatment." (PMID 24452274, 2014). "The CSTB at mRNA and protein levels in two types of epithelial ovarian cancer cells, OVCAR-3 and SK-OV-3, was decreased after TGF-β1 treatment detected by quantitative PCR and western blot analysis, respectively." (PMID 24452274, 2014). "Large increases of procathepsin B level (about 13-fold, p<0.001) and to a lesser degree of cystatin C (1.8-fold, p<0.05) and cystatin B levels (1.4 fold, p<0.001) were revealed in ascites fluids of patients with ovarian cancer compared to the control serum." (PMID 23986888, 2013). "Simultaneously, serum concentration of cystatin B in ovarian cancer (stages II–IV) was slightly elevated (p<0.05) versus serum of patients with a benign tumour." (PMID 23986888, 2013). "Serum cystatin B level increased up to 1.7-fold in the ovarian cancer group compared to the control group." (PMID 23986888, 2013). "Cystatin B in ascites fluid increased equally in both ovarian cancer (p<0.001) and benign ovarian tumours group (p<0.05)." (PMID 23986888, 2013). "Cystatin B was proposed as a biomarker in various tumors like bladder and ovarian cancer." (PMID 39201484, 2024). "In the present study we revealed the expression of CSTB associated with clinicopathological features in human epithelial ovarian cancer and examined for the first time the expression of CSTB regulated by the TGF-β signaling pathway in ovarian cancer cells." (PMID 24452274, 2014). "Furthermore, we examined for the first time the regulation of CSTB expression mediated by the TGF-β signaling pathway in ovarian cancer cells." (PMID 24452274, 2014). "In our study, the level of cystatin B increased in abdominal exudate in benign tumours (compared to the control serum, p<0.05), as well as in ascetic fluids (p<0.001 vs. serum of the control group) in ovarian cancer of stages II–IV." (PMID 23986888, 2013). "This suggests that the role for CSTB in tumor invasion in chickens may be similar to that in human ovarian cancer." (PMID 20727192, 2010). "Next, we blocked the TGF-β signaling pathway by treating ovarian cancer cells with a special TGF-β type I receptor kinase inhibitor, SB-431542, to see if the regulation of CSTB expression is mediated by the TGF-β signaling pathway." (PMID 24452274, 2014). "However, statistical analysis of the immunoreactive scores of CSTB protein between the types of tissues indicated that the expression of CSTB protein was different between the four groups: the normal ovarian tissue, ovarian benign tumor, ovarian borderline tumor and ovarian malignant tumor." (PMID 24452274, 2014). "Since TGF-β plays a key role in ovarian tumorigenesis and since CSTB was overexpressed in ovarian cancer, we subsequently investigated whether TGF-β1 affects CSTB protein expression." (PMID 24452274, 2014). "In general, the change in serum protease inhibitor cystatin B was milder as compared to CA-125 and procathepsin B. Moreover, serum cystatin B level had a tendency to increase (p<0.05 vs. serum in the control group) only in ovarian cancer, not in benign ovarian tumours." (PMID 23986888, 2013).
Alzheimer disease (5 papers, 2021 to 2025). A progressive, neurodegenerative disease characterized by loss of function and death of nerve cells in several areas of the brain leading to loss of cognitive function such as memory and language. "Here we compared the biology of cathepsin B and CSTB in individuals who had Down syndrome and Alzheimer’s disease, with disomic individuals who had Alzheimer’s disease or were ageing healthily." (PMID 37580797, 2023). "The genes associated with Alzheimer’s disease were Erb-B2 receptor tyrosine kinase 2 (ERBB2), Cystatin B (CSTB), and Caspase 6 (CASP6)." (PMID 34379632, 2021). "Alzheimer disease patients showed also significantly higher levels of α-defensins 1–4, Tβ4, cystatin A, and the dimeric and glutathionylated proteoforms of cystatin B." (PMID 34121996, 2021). "Cystatin B is a small, multifunctional protein involved in the regulation of inflammation, innate immune response, and neuronal protection and found highly abundant in the brains of patients with Alzheimer’s disease (AD)." (PMID 36983903, 2023). "The impact of the additional copy of CSTB on Alzheimer’s disease development in people who have Down syndrome is not well understood." (PMID 37580797, 2023). "We find that the abundance of CSTB is significantly increased in the brains of individuals who have Down syndrome and Alzheimer’s disease compared to disomic individuals both with and without Alzheimer’s disease." (PMID 37580797, 2023).
breast carcinoma (5 papers, 2014 to 2026). "CSTB deficiency increases the sensitivity of cells to oxidative stress in cerebellar granule neurons or breast cancer primary cells." (PMID 34504787, 2021). "In cancer research, CSTB deficiency reduces tumor growth via the sensitization of tumor cells to oxidative stress in a breast cancer model." (PMID 24452274, 2014). "For instance, CSTB was increased in HCC, epithelial ovarian tumors, and breast cancer, while decreased in laryngeal squamous cell carcinoma and ESCC." (PMID 34504787, 2021). "For instance, CSTB seems to be upregulated in HCC, epithelial ovarian tumors, and breast cancer, but downregulated in ESCC and laryngeal squamous cell carcinoma (another certain kind of HNSCC)." (PMID 34504787, 2021).
Down syndrome (5 papers, 2011 to 2025). "Cystatin B (CstB), encoded on chromosome 21, is an endogenous inhibitor of cathepsin B. Down syndrome patients show increased expression of CstB, which correlates with early-onset AD risk." (PMID 40869205, 2025). "In mouse and human cellular preclinical models of Down syndrome, three-copies of CSTB increases CSTB protein abundance but this is not sufficient to modulate cathepsin B activity." (PMID 37580797, 2023).
gastric cancer (5 papers, 2021 to 2025). A primary or metastatic malignant neoplasm involving the stomach. "Salivary proteins cystatin B (CSTB), triosephosphate isomerase (TPI1), and deleted malignant brain tumors 1 protein (DMBT1) have all been associated to gastric cancer." (PMID 40005360, 2025). "The published article titled “CSTB Downregulation Promotes Cell Proliferation and Migration and Suppresses Apoptosis in Gastric Cancer SGC-7901 Cell Line” has been retracted from Oncology Research, Vol." (PMID 41179300, 2025). "For instance, knockdown of CSTB in an epithelial ovarian cancer cell line inhibited cell proliferation and promoted apoptosis, whereas the opposite result was found in a gastric cancer cell line." (PMID 34504787, 2021). "Our analysis identified a range of biomarkers, highlighting three proteins - cystatin-B (CSTB), triosephosphate isomerase (TPI1), and deleted in malignant brain tumors 1 protein (DMBT1) - as particularly accurate for gastric cancer diagnosis." (PMID 39119128, 2024). "However, the combination of CSTB, TPI1, and DMBT1 proteins demonstrated the highest AUC value, indicating superior discriminative capacity between gastric cancer patients and healthy individuals." (PMID 39119128, 2024).
hepatocellular carcinoma (5 papers, 2014 to 2026). A malignant tumor that arises from hepatocytes. "Cystatin B (CSTB) is highly expressed in hepatocellular carcinoma (HCC) tissues and serum, indicating its potential as an early diagnostic biomarker." (PMID 41578084, 2026). "CSTB is aberrantly expressed in a range of neoplastic tissues, including hepatocellular carcinoma, pancreatic ductal adenocarcinoma, and cervical cancer." (PMID 39996856, 2025). "Elucidating the molecular characteristics of CSTB may provide a viable avenue for developing novel therapeutic interventions for hepatocellular carcinoma." (PMID 41578084, 2026). "Our findings demonstrate that CSTB plays a critical role in hepatocellular carcinoma (HCC) progression." (PMID 41578084, 2026). "Notably, CSTB mRNA and protein expression levels were significantly elevated in hepatocellular carcinoma (HCC) tissues compared to normal tissues." (PMID 41578084, 2026).
lung carcinoma (5 papers, 2014 to 2025). "CSTB expression was inversely correlated with lung cancer stage, tumor grade, and a more unfavorable prognosis." (PMID 36816947, 2023). "Emerging evidence indicates that Cystatin B may inhibit tumor invasion through its effects on cathepsin activity and could serve as a prognostic marker in lung cancer." (PMID 40641363, 2025). "Of these, Cathepsin B (CTSB), Protein disulfide–isomerase (P4HB) and Cystatin-B (CSTB) were found upregulated in myeloma, lung cancer or colorectal cancer." (PMID 38791048, 2024).
lymph node metastasis (5 papers, 2014 to 2025). "Moreover, they were significantly associated with lymph node metastasis, which, in turn, correlated with advanced clinical staging, with exception of CSTB." (PMID 30185791, 2018). "In addition, CSTB-specific peptides in saliva were associated with lymph node metastasis." (PMID 34504787, 2021). "A study of OSCC emphasized the potential of CSTB-specific peptides in saliva to reflect the status of lymph node metastasis in tumor-bearing patients." (PMID 34504787, 2021). "Other studies of HNSCC/ESCC also reported that a lower concentration of CSTB increased the risks of lymph node metastasis and local tumor recurrence and may thus result in a shorter DFS." (PMID 34504787, 2021). "Interestingly, SRM-MS analysis showed CSTB, LTA4H, PGK1, COL6A1, ITGAV, and NDRG1 were significantly downregulated in patients with lymph node metastasis." (PMID 30185791, 2018). "By comparing the clinicopathological features of patients with epithelial-type tumors of the ovary, we found that CSTB was not correlated with age, histological types, tumor size and stage, and lymph node metastasis." (PMID 24452274, 2014). "In summary, a sensitive electrochemical biosensor was successfully developed to detect and quantify CSTB, LTA4H, and COL6A1 biomarkers in noninvasive saliva samples from OSCC patients, with and without lymph node metastasis." (PMID 40728373, 2025).
myoclonic epilepsy (5 papers, 2011 to 2022). A group of epilepsy syndromes in which myoclonic seizures are a prominent feature. "Unverrich‐Lundborg disease (EPM1) is an autosomal recessive progressive myoclonic epilepsy caused by mutations in CSTB, which encodes cystatin B, a cysteine protease inhibitor." (PMID 32783192, 2020). "Stefin B (cystatin B) is an intracellular inhibitor of cysteine cathepsins and mutations in the stefin B gene, resulting in the development of Unverricht–Lundborg disease, which is a form of myoclonic epilepsy." (PMID 31766320, 2019).
colon cancer (4 papers, 2015 to 2025). "As anticipated, the expression of the risk gene CSTB in colon cancer cells was significantly higher than in NCM460 cells." (PMID 40959081, 2025). "Cystatin B (CSTB) is a cysteine protease inhibitor that is poorly expressed in lung and colon cancers with poor prognosis." (PMID 37538932, 2023).
glioma (4 papers, 2015 to 2024). A benign or malignant brain and spinal cord tumor that arises from glial cells (astrocytes, oligodendrocytes, ependymal cells). "In glioma cells, H-1PV can induce lysosome-dependent cell death, with the regression of the two cathepsin inhibitors, cystatin B and C, enabling the virus to overcome the resistance of glioma cells to common cytotoxic agents (e.g., cisplatin) or to soluble death ligands (e.g., TRAIL)." (PMID 38396720, 2024). "CSTB upregulation has been described in GBM and GBM stem cells, particularly in IDHwt, and has been strongly associated with the mesenchymal subtype and immunosuppressive conditions in gliomas." (PMID 36076905, 2022). "The other well-predicted genes, including COL5A1, CPA4, CSTB, and PPIC in gliomas and DAK, ITPRIP, TM4SF19, TMEM200A in RCC have not been studied thoroughly in cancer and their roles in cancer worth further investigating." (PMID 32194984, 2020).
myoclonus epilepsy (4 papers, 2006 to 2024). "Moreover, earlier studies on families affected by myoclonus epilepsy of Unverricht and Lundborg (EPM1; CSTB mutations; OMIM 254800) reported mild symptoms in heterozygous carriers of the disease allele." (PMID 22032306, 2011).
pancreatic cancer (4 papers, 2022 to 2025). "Consistent with our study, several studies have reported increased CSTB, MIF, and KRT19 levels in pancreatic cancer." (PMID 40289610, 2025).
Sepsis (4 papers, 2015 to 2023). Sepsis is defined as life-threatening organ dysfunction caused by a dysregulated host response to infection. "According to Maher’s findings (2014), the CSTB-deficient mice were significantly more sensitive to the lethal LPS-induced sepsis and could secrete higher amounts of pro-inflammatory cytokines IL-1β and IL-18." (PMID 33926569, 2021).
acute kidney injury (3 papers, 2020 to 2024). Sudden and sustained deterioration of the kidney function characterized by decreased glomerular filtration rate, increased serum creatinine or oliguria. "Genetics: In the first years, she underwent different genetic testing (Sanger sequencing) in order to exclude Unverricht–Lundborg disease (cystatin B, CSTB), PME with renal failure (SCARB2), Lafora disease (laforin—EPM2A, and malin—NHLRC1)." (PMID 32752208, 2020).
colorectal cancer (3 papers, 2014 to 2024). A primary or metastatic malignant neoplasm that affects the colon or rectum. "On the other hand, increased CSTB has been observed in various cancers such as lung, hepatocellular and colorectal cancers." (PMID 24452274, 2014).
COVID-19 (3 papers, 2021 to 2024). A disease caused by infection with severe acute respiratory syndrome coronavirus 2. "Previously, we showed that the proinflammatory subtype of monocytes (Mon IFI30) accompanies severe Delta COVID-19, and this population yields high expression of IFI30, C15orf48, CXCL8, CSTB, and SPP1 genes." (PMID 39712003, 2024). "This module included the NUPR1 stress response gene as well as CSTB, which is an inhibitor of cathepsins like CTSL and CTSB that are involved in COVID-19 viral entry." (PMID 35007307, 2022).
epithelial ovarian tumors (3 papers, 2014 to 2021). "In human epithelial ovarian tumors, cystatin B was a progression marker, which was associated with the transforming growth factor β (TGF-β) signaling pathway." (PMID 31692912, 2019). "In conclusion, CSTB was overexpressed in human epithelial ovarian tumors, including serous, mucinous and clear cell tumors." (PMID 24452274, 2014). "Next we examined whether the expression of CSTB is correlated with the clinicopathological features of patients with epithelial ovarian tumors." (PMID 24452274, 2014).
kidney damage (3 papers, 2020 to 2025). "Recently, an assay for the tubular biomarker urinary cystatin B was commercialized to assess for active kidney damage in dogs and cats." (PMID 40008829, 2025). "A preliminary evaluation of some biomarkers of kidney damage (clusterin, cystatin B, inosine and NGAL) has been reported previously." (PMID 36196592, 2022).
Obesity (3 papers, 2022 to 2025). Accumulation of substantial excess body fat. "Pregnant women with obesity and generalized gingival bleeding exhibited notably higher expression of Cystatin-D (>4-fold), with slight increases in Cystatin-B (1.62-fold), Cystatin-C (1.49-fold), and Cystatin-SN (1.12-fold) compared with G2." (PMID 40366920, 2025). "Similar results were found at the follow up visit for a subset (N = 80) of participants, and five proteins were elevated in the obesity group compared to NOH group, four of which (LEP, CSTB, FABP4 and SSCAD) were also identified in the baseline." (PMID 38548792, 2024). "The reliable link between Cystatin-B and obesity is not yet clear." (PMID 35813634, 2022).
viral infection (3 papers, 2021 to 2022). "To define the players that could be involved in ZIKV infection in the placenta, we explored the expression of proteins previously associated with other viral infections and innate immunity, namely CSTB, RAGE, and AXL." (PMID 36429055, 2022).
Atrophy (2 papers, 2009 to 2014). Any weakening or degeneration, especially through lack of use. "Additionally, mouse studies demonstrate that EPM1 heterozygosity results in lower cystatin B expression than wild-type mice and is associated also with near-universal mild neurogeneration and neuronal atrophy." (PMID 19656408, 2009). "It is caused by mutations in the gene encoding cystatin B. Previously, widespread white matter changes and atrophy has been detected both in adult EPM1 patients and in 6-month-old cystatin B–deficient mice, a mouse model for the EPM1 disease." (PMID 24603771, 2014).
celiac disease (2 papers, 2020 to 2024). An autoimmune genetic disorder with an unknown pattern of inheritance that primarily affects the digestive tract. "Purkinje cells are involved pathologically in coeliac disease, ET, and PHM, and expression of cystatin B, SCGE 11b, and the GHB receptor are selectively increased in Purkinje cells." (PMID 33178485, 2020).
dementia (2 papers, 2023). Loss of intellectual abilities interfering with an individual's social and occupational functions. "The abundance of CSTB was significantly higher in cases of people who had AD-DS than in those from the general population who had EOAD or those that did not have dementia (healthy ageing)." (PMID 37580797, 2023).
depression (2 papers, 2018 to 2023). "Further, there was evidence of significant interactions between chronic sexual abuse and current depression for IL-1α, IP-10, Serpin A1, Cystatin B, and FGF." (PMID 29894487, 2018).
liver cancer (2 papers, 2021 to 2022). An epithelial or non-epithelial malignant neoplasm that arises from the liver. "Conversely, high expression of CSTB, an endogenous inhibitor of lysosomal cathepsins, and p62/SQSTM1, was related to poor prognosis of liver cancer." (PMID 33803301, 2021).